HOXD9 (homeobox D9)
Description:
Sequence-specific transcription factor which is part of a developmental regulatory system that provides cells with specific positional identities on the anterior-posterior axis.
Synonyms: HOX4C; HOX4; Hox-4.3; Hox-5.2
Tractability: No criterion of Open Targets' tractability assessment is met for any kind of drug.
Gene: Protein-coding gene on chromosome 2 (176,122,719 to 176,124,937, forward strand). Ensembl gene ENSG00000128709.
Subcellular location: Nucleus
Subcellular location (Human Protein Atlas): Nucleoli; Nucleoplasm
Gene Ontology:
Molecular function: DNA-binding transcription repressor activity, RNA polymerase II-specific; RNA polymerase II transcription regulatory region sequence-specific DNA binding; sequence-specific double-stranded DNA binding; DNA-binding transcription factor activity; DNA-binding transcription factor activity, RNA polymerase II-specific; RNA polymerase II cis-regulatory region sequence-specific DNA binding; DNA binding
Biological process: negative regulation of transcription by RNA polymerase II; anterior/posterior pattern specification; embryonic skeletal system morphogenesis; proximal/distal pattern formation; regulation of transcription by RNA polymerase II; DNA-templated transcription; regulation of DNA-templated transcription
Cellular component: nucleolus; nucleoplasm; chromatin; nucleus
Genetic constraint (gnomAD): Loss-of-function variants: 21 observed, 18.13 expected, observed/expected ratio (o/e) 1.16, 90% interval 0.82 to 1.65. The synonymous counts are far from expectation, so gnomAD's model fits this gene poorly and the ratio says little. Missense variants: 503 observed, 405.97 expected, observed/expected ratio (o/e) 1.24, 90% interval 1.15 to 1.33. Synonymous variants: 240 observed, 176.92 expected, observed/expected ratio (o/e) 1.36, 90% interval 1.22 to 1.51.
Homologues: Orthologues: chimpanzee HOXD9 (98% identical), macaque HOXD9 (93% identical), pig HOXD9 (89% identical), guinea pig HOXD9 (88% identical), mouse Hoxd9 (85% identical), rat Hoxd9 (85% identical), dog HOXD9 (81% identical), rabbit HOXD9 (54% identical), tropical clawed frog hoxd9 (51% identical), zebrafish hoxd9a (45% identical). Paralogues in human: HOXC9 (41% identical), HOXB9 (36% identical), HOXA10 (28% identical), HOXD10 (26% identical), HOXC10 (23% identical), HOXC12 (21% identical), HOXD12 (20% identical), HOXA1 (19% identical), HOXC11 (19% identical), HOXA4 (18% identical), HOXD4 (18% identical), HOXA11 (18% identical), and 30 more.
Diseases named in the same sentence as HOXD9 in open-access papers:
HOXD9 is named in the same sentence as 61 diseases in open-access papers, as found by Europe PMC text mining. Sharing a sentence is not in itself a finding about the gene and the disease. The quoted sentences say what the papers report.
glioma (11 papers, 2011 to 2023). A benign or malignant brain and spinal cord tumor that arises from glial cells (astrocytes, oligodendrocytes, ependymal cells). "Particularly, HOXD9 is associated with several cancers, including gliomas, esophageal cancer, gastric cancer, and hepatocellular carcinoma." (PMID 37974228, 2023). "Prior research has demonstrated that HOXD9 has the capacity to augment the proliferation of lung cancer, glioma, and other cellular entities, while concurrently impeding the tumor cell apoptosis." (PMID 37974228, 2023). "Functional analysis in human gliomas suggested that HOXD9 deletion induced apoptosis via downregulation of anti-apoptotic factor B-cell lymphoma-2 (BCL-2) and upregulation of tumor necrosis factor-related apoptosis-inducing ligand (TRAIL)." (PMID 36907878, 2023). "Many HOMEOBOX (HOX)-related genes (HOXD11, HOXD9, HOXC10, HOXC11, HOXC6, HOXB3, HOXA2, HOXA1) were associated with a glioma grade and significantly overexpressed in GIV (Wilcoxon rank-sum and BH padj < 0.05)." (PMID 36850002, 2023). "The HOXD9 encourages proliferation and invasion/ migration of cervical, esophageal, glioma, liver, and tumor cells." (PMID 32281284, 2020). "Studies have demonstrated that HOXD9 contributes to both cell proliferation and/or cell survival in gliomas." (PMID 31547840, 2019). "As a member of the HOX family, HOXD9 has been found to be deregulated in several cancers including cervical, glioma ovarian and liver cancers." (PMID 31547840, 2019). "To investigate the role of HOXD9 in gliomas, we silenced its expression in the glioma cell line U87 using HOXD9-specific siRNA, and observed decreased cell proliferation, cell cycle arrest, and induction of apoptosis." (PMID 21600039, 2011). "In the present study, we demonstrated that HOXD9 was highly expressed in glioma cells and GCSCs cultured from patient specimens compared with human NSPCs and astrocytes." (PMID 21600039, 2011). "Bioinformatic analysis of data collected from published transcriptomes suggests an increase of HOXD9 expression in gliomas and more particularly in glioblastomas as compared to the normal brain tissues and medulloblastomas." (PMID 21600039, 2011). "We found that HOXD9 was more highly expressed in gliomas and GCSCs and that gene silencing of HOXD9 reduced the proliferation of both glioma cells and glioma cancer stem-like cell population." (PMID 21600039, 2011). "We evaluated the cell division time and morphological changes in U87 glioma cells after HOXD9 siRNA transfection using a time-lapse video microscope system according to our previous study." (PMID 21600039, 2011). "HOXD9 contributes to cell proliferation and/or survival in glioma cells and glioma cancer stem-like cells." (PMID 21600039, 2011). "In this study, we analyzed the expression and function of HOXD9 in human gliomas and found high expression of HOXD9 in GCSCs." (PMID 21600039, 2011). "In fact, knockdown of HOXD9 decreased the proliferation of glioma cancer stem-like cells in vitro, supporting the idea." (PMID 21600039, 2011). "In this study, we found high expression of the HOXD9 gene transcript in glioma cell lines and human glioma tissues by quantitative real-time PCR." (PMID 21600039, 2011). "For instance, miR-205 downregulates HOXD9 to suppress EMT in human glioma." (PMID 37974228, 2023). "Previous studies have revealed that HOXD9 promoter methylation is higher in tumors than in healthy tissue and that DNA methylation levels correlate with the expression of HOXD9 mRNA and protein in malignant melanoma and glioma." (PMID 36397165, 2022). "However, high expression of HOXD9 transcript and protein was observed in glioma cell lines and brain tumor tissues suggesting the contribution of HOXD9 in cell proliferation and/or survival." (PMID 30832707, 2019).
glioma (continued). "It was also found that HOXD9 could promote the proliferation of glioma cells and inhibit cell apoptosis, the research identified the high expression of HOXD9 functioned as an enriched-cell fraction of glioma cancer stem-like cells." (PMID 29383189, 2017). "HOXD9 may be useful as a marker for glioma and GCSCs, and therapies targeting HOXD9 should be considered for further development." (PMID 21600039, 2011). "In this point, HOXD9 may be an ideal therapeutic target for the treatment of gliomas because the expression in NSPCs and astrocytes is lower than GCSCs, suggesting that HOXD9 targeted therapy may have a therapeutic index." (PMID 21600039, 2011). "In the future, it may be important to evaluate the methylation status of HOXD9 in the whole genome, as well as histone modification in gliomas and GCSCs compared with normal brain and NSPCs using the tiling array system and/or a next-generation sequencer." (PMID 21600039, 2011). "Our results suggest that HOXD9 may be a novel marker of GCSCs and cell proliferation and/or survival factor in gliomas and glioma cancer stem-like cells, and a potential therapeutic target." (PMID 21600039, 2011). "Furthermore, gene silencing of HOXD9 reduced the number of colony formation in U87 glioma cells compared to the control." (PMID 21600039, 2011). "This is the first study examining the function of HOXD9 in gliomas." (PMID 21600039, 2011). "Thus, the analyses of epigenetic regulation of HOXD9 gene expression in gliomas and GCSCs related to Polycomb proteins and non-coding RNA will be an important issue in the near future." (PMID 21600039, 2011). "In this study, gene silencing of HOXD9 induced apoptosis and reduced the expression of BCL-2 in glioma cells, indicating that HOXD9 may support the cell survival." (PMID 21600039, 2011). "Moreover, caspase-3/7 activity was shown to be elevated in HOXD9-silenced glioma cells." (PMID 36907878, 2023). "Thus, HOXD9 may be a new target for the treatment of gliomas based on GCSC population." (PMID 21600039, 2011). "We also examined the expression of HOXD9 mRNA in four glioma cell lines, U87, SK-MG-1, KNS-42 and KNS-81 and found higher expression of HOXD9 mRNA compared with that in normal human astrocytes (33-, 32.5-, 52.8-, and 57.5-fold higher, respectively)." (PMID 21600039, 2011). "We showed that gene knockdown of HOXD9 reduces the proliferation of U87, KNS-42, and KNS-81 glioma cells and glioma cancer stem-like cells; SK-MG-1 SP cells." (PMID 21600039, 2011). "High expression of HOXD9 was reported in SK-MG1 cells and in human glioma cancer stem cells." (PMID 27244890, 2016). "To investigate the role of HOXD9 in tumor cells, we examined changes in U87 glioma cell proliferation in the absence of HOXD9 using siRNA." (PMID 21600039, 2011). "In addition, the decrease of cell proliferation by HOXD9 gene silencing was observed in KNS-42 and KNS-81 glioma cells." (PMID 21600039, 2011).
gastric cancer (8 papers, 2019 to 2024). A primary or metastatic malignant neoplasm involving the stomach. "Recent investigations have noticed that HOXD9 is abnormally expressed in many cancers, such as gastric cancer, hepatocellular carcinoma, and thyroid cancer." (PMID 39511608, 2024). "HOXD9 expression was elevated in several types of cancers, such as glioblastomas, cervical cancer, colorectal carcinoma, gastric cancer, hepatocellular carcinoma and esophageal squamous cell carcinomas." (PMID 36907878, 2023). "Clinically, elevated levels of HOXD9 have been detected in various cancers, such as glioblastomas, cervical cancer, colorectal carcinoma, gastric cancer, hepatocellular carcinoma, and esophageal squamous cell carcinomas." (PMID 36907878, 2023). "By exploring the regulatory mechanism of HOXD9 on a molecular level, HOXD9 overexpression was found to significantly enhance the migration, invasion, and metastasis of hepatoma cells, gastric cancer cells, cervical cancer cells, and CRC cells." (PMID 33579281, 2021). "Next, we examined the expression of HOXD9 in the following seven gastric cancer cell lines: AGS, BGC-823, MGC-803, HGC-27, MKN-28, MKN-45, SGC-7901 and immortalized gastric mucosal epithelial cell line GES-1." (PMID 31547840, 2019). "The expression of the HOXD9 protein level in gastric cancer cells was significantly higher than the expression of GES-1." (PMID 31547840, 2019). "To test the role of RUFY3 in HOXD9-mediated tumor progression, we have established tail-vein metastasis model and orthotropic implantation model using human gastric cancer AGS cells in nude mice, which resulted in lung and liver metastases." (PMID 31547840, 2019). "In addition, another observation elucidate that knockdown of HOXD9 in vitro effectively inhibited the proliferation, migration, and invasion of gastric cancer (GC) cells." (PMID 39511608, 2024). "Whereas in gastric cancer, HOXD9 could influence the proliferation, migration, and invasiveness of cells by interacting with the promoter of RUFY3." (PMID 37974228, 2023). "However, the role of HOXD9 in the growth and metastasis of gastric cancer (GC) remains to be elucidated." (PMID 31547840, 2019).
cervical cancer (7 papers, 2021 to 2023). A primary or metastatic malignant neoplasm involving the cervix. "HOXD9 is upregulated in cervical cancer species, is strongly associated with metastasis rate and poor prognosis in cervical cancer patients, and stimulates the migration and invasive ability of cervical cancer cells by positively regulating HMCN1 levels." (PMID 36213580, 2022). "In addition, high level of HOXD9 has been closely linked to metastasis rate and poor prognosis in cervical cancer patients." (PMID 36397165, 2022). "In cervical cancer, HOXD9 was found to bind to the promoter of the P97 oncogene to regulate the expression of the human papillomavirus 16 E6/E7 genes and thereby promote survival, proliferation, and metastasis of cervical cancer cells." (PMID 37974228, 2023). "In summary, suppression of HOXD9 in cervical cancer can simultaneously suppress the HPV oncogenes E6 and E7, arrest cell proliferation, and induce cell death." (PMID 34572841, 2021). "The HOXD9 knockdown suppressed the E6/E7 gene expression in HPV18-positive cervical cancer cells." (PMID 34572841, 2021). "In this article, we investigated whether HOXD9 regulated the P105 promoter of HPV18 and examined the role of HOXD9 in intracellular signaling of cervical cancer (CC)." (PMID 34572841, 2021). "Our results indicate that HOXD9 has pivotal roles in the proliferation and immortalization of HPV18-positive cervical cancer cells through activating the P105 promoter." (PMID 34572841, 2021).
hepatocellular carcinoma (7 papers, 2019 to 2024). A malignant tumor that arises from hepatocytes. "The overall association scores for hepatocellular carcinoma were 0.210 for HOXD9, 0.174 for NDST3, 0.111 for PZP, 0.106 for E2F8, 0.061 for ADRA2B, and 0.029 for COL15A1." (PMID 31754347, 2019). "HOXD9 promotes epithelial-mesenchymal transition and metastasis in hepatocellular carcinoma and colorectal carcinoma." (PMID 38907278, 2024). "HOXD9 enhances hepatocellular carcinoma (HCC) cell migration, invasion, and metastasis via the ZEB1 gene expression." (PMID 34572841, 2021). "In hepatocellular carcinoma (HCC), HOXD9 was found to promote epithelial–mesenchymal transition (EMT) by interacting with the promoter of ZEB1." (PMID 37974228, 2023).
breast carcinoma (6 papers, 2015 to 2025). "Other genes we replicated have been reported to play a role in breast cancer progression such as HOXD9, TDRD10, SH3PXD2A and TSPAN15, although these studies did not involve DNA methylation data as a prognostic marker." (PMID 39825380, 2025). "A total of 1799 differentially methylated regions were identified, including ZNF154, BCL9, and HOXD9, in which significant methylation differences were confirmed in breast cancer patients through a quantitative real-time polymerase chain reaction." (PMID 34452548, 2021). "This study may provide a novel insight for the treatment of breast cancer through targeting miR-205/HOXD9/Snail1." (PMID 33428601, 2021). "In addition to our findings, because of hypomethylation and overexpression of HOXD9 in young breast cancer tissues." (PMID 34452548, 2021). "In summary, the results showed that the methylation pattern of HOXD9, ZNF154, and BCL9 genes in peripheral blood leukocytes could be used as a potential biomarker for breast cancer risk assessment." (PMID 34452548, 2021). "The present study may provide a novel insight for the therapeutic strategies of breast cancer through targeting miR-205/HOXD9/Snail1." (PMID 33428601, 2021). "The present study may provide a novel thought for the treatment of breast cancer by targeting miR-205/HOXD9/Snail1." (PMID 33428601, 2021). "However, whether miR-205 could affect HOXD9 expression and further influence breast cancer cells viability remain unknown." (PMID 33428601, 2021). "However, the role of miR-205 and HOXD9 in breast cancer remains unclear." (PMID 33428601, 2021). "Three novel DMRs located in promoter regions of HOXD9, ZNF154, and BCL9 genes were confirmed in the peripheral blood of breast cancer patients." (PMID 34452548, 2021). "Meanwhile, HOXD9 could be regulated by miR-126, and miR-10b can interact with HOXD10 to promote breast cancer metastasis." (PMID 33428601, 2021).
cholangiocarcinoma (4 papers, 2019). A carcinoma that arises from the intrahepatic biliary tree (intrahepatic cholangiocarcinoma) or from the junction, or adjacent to the junction, of the right and left hepatic ducts (hilar cholangiocarcinoma). "For example, significant differences in the methylation levels of OPCML and HOXD9 were observed in serum cell-free DNA from CCA patients, and these two genes can be used for the differential diagnosis between cholangiocarcinoma and other biliary diseases." (PMID 31889904, 2019).
glioblastoma (4 papers, 2011 to 2023). The most malignant astrocytic tumor (WHO grade IV). "Using immunohistochemistry, we observed HOXD9 protein expression in human brain tumor tissues, including astrocytomas and glioblastomas." (PMID 21600039, 2011).
liver cancer (4 papers, 2018 to 2024). An epithelial or non-epithelial malignant neoplasm that arises from the liver. "The model of SPP1 combined with centromere protein A (CENPA), melanoma-associated antigen family member B6 (MAGEB6), and homeobox D9 (HOXD9) can predict the overall survival in liver cancer patients." (PMID 38374893, 2024). "HOXD9 leads to mesenchymal‐epithelial transition (MET), and silencing HOXD9 promotes MET in liver cancer cells." (PMID 30247807, 2018).
lung carcinoma (4 papers, 2019 to 2023). "In addition to HOXA9, the methylation of HOXB4, HOXD8, and HOXD9 were also different between tumor and adjacent normal tissues in lung cancer." (PMID 31850197, 2019). "In order to gain insight into the role of ITF2 regulating the expression of HOXD9 in NSCLC, we overexpressed ITF2 in H23 resistant lung cancer cells." (PMID 32224864, 2020).
lymph node metastasis (4 papers, 2017 to 2023). "Previous study in melanoma patients with lymph node metastasis showed the association of hypermethylated HOXD9 with poor prognosis." (PMID 30832707, 2019). "A study investigating differentially methylated CpG sites between melanoma brain metastases (poor prognosis) and lymph node metastasis from patients with good prognosis reported that HOXD9 methylation was associated with overall survival." (PMID 28396701, 2017). "In a validation cohort of 145 melanoma patients, HOXD9 hypermethylation in lymph node metastases was associated with shorter progression-free and overall survival." (PMID 28396701, 2017). "Besides, melanoma patients with hypermethylated HOXD9 in lymph node metastasis showed poorer disease-free and overall survival." (PMID 30832707, 2019).
melanoma (4 papers, 2016 to 2022). A malignant, usually aggressive tumor composed of atypical, neoplastic melanocytes. "Promoter DNA methylation of HOXD9 at a region from − 753 to + 193 bp of the TSS decreased its expression in melanoma." (PMID 30832707, 2019). "By contrast, low expression of HOXD9 transcript and protein due to promoter hypermethylation was noticed in melanoma brain metastasis by which DNA methylation of HOXD9 was significantly higher than that in early stages." (PMID 30832707, 2019). "The function of HOXD9 in melanoma is incompletely understood, but studies from HCC suggest that it significantly enhances migration, invasion, and metastasis." (PMID 28396701, 2017). "In brain metastases from melanoma, DNA methylation was altered and the significantly affected genes were the homeobox family members, especially for HOXD9." (PMID 27160082, 2016).
colorectal carcinoma (3 papers, 2020 to 2024). A malignant epithelial neoplasm that arises from the colon or rectum and invades through the muscularis mucosa into the submucosa. "To investigate the mechanism by which HOXD6 contributes to colorectal cancer progression, we constructed stable transfectants using HOXD9‐sense plasmids or knockdown of HOXD9 with shRNA in LoVo and SW1116 cells and was confirmed by western blot analysis." (PMID 32281284, 2020).